SSX2 (SSX family member 2)
Diseases named in the same sentence as SSX2 in open-access papers (continued):
Sharing a sentence is not in itself a finding about the gene and the disease.
melanoma (continued). "SSX proteins are expressed in about 30% of melanomas and having demonstrated that ectopic SSX2 expression regulated PcG nuclear body formation in A375 melanoma cells, we next investigated the effect of SSX2 on PcG function in melanoma cells with endogenous SSX expression." (PMID 25249625, 2014). "Interestingly SSX2 was detected in almost all melanoma tissues and derived cell lines (95%) compared to SSX4 (57%), SSX1 (38%), SSX5 (33%) and SSX3 (19%) expression." (PMID 24787708, 2014). "As SSX2 is expressed in multiple types of human cancer, including 30% of melanomas, this protein may be an important player in the chromatin reprogramming instrumental for cancer development." (PMID 25249625, 2014). "Evidence of SSX2 immunogenicity includes the detection of SSX2-specific antibodies in the serum of patients with melanoma, colon cancer and breast cancer and the presence of CD8 T cells with specificity for SSX2 in tumor-infiltrated lymph nodes of patients with melanoma and hepatocarcinoma." (PMID 24681846, 2014). "Published studies have explored the combination of single or dual CTLA4/PD-1 inhibitors and MYB oncoprotein targeting DNA vaccines, SSX2 cancer antigen, PSMA prostate-specific antigen, and TRP-2 and gp100 melanoma-specific antigens." (PMID 37138873, 2023). "In accordance with previous small cohort studies, the highest occurrence and expression levels were observed for SSX1 and SSX2, with 89% of primary melanomas and 88% of metastases having expression of either SSX1, SSX2 or both." (PMID 36276095, 2022). "To test the ability of these TCRs to recognize the endogenous SSX2 expressed by tumor cells, we cultured PBLs (transduced with TCR-5, -8, -9, -11) with cell lines derived from melanoma (888, SKMEL-23, 624), glioma (U251), and breast cancer (MCF-7)." (PMID 24681846, 2014). "This strongly indicates that endogenous SSX2 indeed inhibits BMI1 PcG body formation and repressive function in FM45 melanoma cells." (PMID 25249625, 2014). "This epitope was mapped to aa 19–34 of SSX2 using truncated peptide assays and was recognized by CD4+ T cells from an SSX2-expressing melanoma patient." (PMID 20981248, 2010). "Recognition of this epitope by melanoma-reactive CTL clone LAU 50/4D7 was confirmed by cytotoxicity assay, and interestingly, the native SSX2 peptide p41–49 had recognition that was in the same range as the optimal peptide." (PMID 20981248, 2010). "Resembling the clinical melanoma samples, all SSX genes could be detected in FM6, FM79 and CBK14797 before knockdown, but the expression was dominated by SSX1 and SSX2." (PMID 36276095, 2022). "SSX2 was originally identified as part of a genomic translocation present in synovial sarcoma and later found to be identical to HOM-MEL-40, an immunogenic protein known to induce spontaneous antibody responses in 10% of patients with melanoma." (PMID 24681846, 2014). "Ectopic expression of SSX2 in A375 melanoma cells did not affect the overall level of H3K27me3, but the level was, however, slightly increased in FM45 cells with reduced SSX2 expression." (PMID 25249625, 2014). "They found that SSX2 p41–49-specific CTLs were identifiable in both melanoma patients and healthy donors, although at lower frequency in healthy donors or patients with SSX2-negative tumors." (PMID 20981248, 2010). "Since FM45 melanoma cells are SSX2/3-positive and do not contain BMI1 PcG bodies, we investigated whether SSX2 is, in fact, responsible for the absence of BMI1 bodies in these cells." (PMID 25249625, 2014). "To investigate whether the SSX2-mediated disintegration of BMI1 and EZH2 nuclear bodies in A375 melanoma cells influenced the repressive function of these proteins, we performed global gene expression profiling of A375 cells with and without ectopic SSX2 expression." (PMID 25249625, 2014).
melanoma (continued). "Interestingly, SSX2 CD4+ T cells failed to recognize IFNγ-treated melanoma cells expressing SSX2 and class II MHC molecules (HLA-DP); however, they were stimulated by antigen-loaded dendritic cells." (PMID 20981248, 2010). "Again, as was found for the SSX2 class II peptides, CD4+ T cells could not recognize melanoma cells directly but were activated by APCs loaded with SSX4 antigen, which suggested that this peptide may not be presented through the endogenous pathway in tumor cells." (PMID 20981248, 2010).
breast cancer (11 papers, 2001 to 2024). A primary or metastatic malignant neoplasm involving the breast. "Yet another study demonstrated antibody response against Synaptonemal complex protein-1 (SCP-1) and Synovial sarcoma X break point 2 (SSX-2) only in 6% and 1% of breast cancer patients." (PMID 23451156, 2013). "In addition, although some of the antigens very specific to BC have been purified up until to now, they are not detectable in most of the sera from women in early stages of BC (i. e., AutoAntibodies (AAb) to NYESO1 are found in 4%, SCP1in 6%, and SSX2 in only 1% of sera from breast cancer patients)." (PMID 25781932, 2015). "Türeci also reported in the same paper that SSX2 was expressed in about 50% of melanoma tumor samples, 30% of hepatocellular carcinoma tumor samples, 25% of colon and prostate cancer samples, 20% of breast cancers, and several other tumor samples of different histological origin examined by RT-PCR." (PMID 20981248, 2010). "Of 16 CTAGs examined in the first panel of 42 breast cancer samples, seven antigens were found not to be expressed in any of the specimens: SSX2, SSX4, CTAG2, CAGE1, MAGEA1, MAGEA4 and MAGEA11." (PMID 17650306, 2007).
prostate carcinoma (5 papers, 2010 to 2022). A carcinoma that arises from epithelial cells of the prostate gland. "In addition to MM, SSX2 expression in prostate cancer has been reported by our group to be associated with advanced-stage prostate cancer." (PMID 20981248, 2010). "SSX2, a prostate cancer-testis antigen, is relatively overexpressed in metastatic prostate cancer as compared with localized prostate cancer or healthy prostate samples." (PMID 34257408, 2022). "Taken together, these data corroborate the finding that SSX2 knockdown increases focal adhesion and migration of a prostate cancer cell line." (PMID 27276714, 2016). "Our data indicate that SSX2 is involved in processes related to EMT in prostate cancer, notably focal adhesion, potentially accounting for the prevalence of expression in circulating tumor cells, but is itself not a driver of EMT." (PMID 27276714, 2016). "Further, we examined SSX2 function in prostate cancer through knockdown and overexpression in prostate cancer cell lines." (PMID 27276714, 2016). "SSX2 knockdown, in the 22Rv1 prostate cancer line, demonstrated a large fold change in many different EMT associated genes (TWIST1, ZEB2, MMP2, VIM, CDH1, CDH2) however these genes did not respond in an anticipated or canonical way." (PMID 27276714, 2016). "This suggests that when SSX2 is expressed in prostate cancer, focal adhesion molecules are downregulated." (PMID 27276714, 2016). "Upon knockdown of SSX2 in the 22Rv1 prostate cancer cell line we found that the SSX2 knockdown cells had less anchorage-independent growth, faster growth rate, increased invasion, and increased tumorigenicity in SCID mice." (PMID 27276714, 2016). "Smith and collaborators isolated T cells that recognized a SSX2 epitope spanning residues 103–111, from a prostate cancer patient." (PMID 24681846, 2014). "Since we detected SSX2 mRNA in the peripheral blood of prostate cancer patients but not healthy controls, we assumed that the detection was of circulating tumor cells expressing SSX2, rather than, for example, cell-free tumor-associated RNA." (PMID 27276714, 2016). "Given the prevalence of SSX2 in the peripheral blood of patients with prostate cancer, we next questioned whether SSX2 expression in prostate cancer cells was similarly associated with markers of EMT." (PMID 27276714, 2016). "Additionally, we found SSX2 is expressed in a CD45−/EpCAM+/CD63+ cell subset in the blood of patients with prostate cancer, a cell subset specifically representing prostate-specific circulating tumor cells." (PMID 27276714, 2016). "In the present work we report the isolation and characterization of human T cell receptors (TCRs) with specificity for synovial sarcoma X breakpoint 2 (SSX2), a cancer/testis antigen expressed in melanoma, prostate cancer, lymphoma, multiple myeloma and pancreatic cancer, among other tumors." (PMID 24681846, 2014). "The potential of SSX2 as an immune target is supported by immunoglobulin G (IgG) responses and CD8+ T cells specific for SSX2 observed in patients with prostate cancer." (PMID 34257408, 2022). "We previously screened the sera of prostate cancer patients against an expression library of 29 CTA family members, and identified SSX2 as one of the most commonly recognized CT antigens." (PMID 27276714, 2016). "Surprisingly, microarray analysis revealed knockdown of SSX2 also resulted in a knockdown of the androgen receptor (AR) and prostate specific membrane antigen (PSMA), both of which are intrinsically tied to prostate cancer disease progression." (PMID 27276714, 2016). "These examples differ from prostate cancer where we predominantly saw only SSX2 expression, and there was no increase in the prevalence of SSX2 expression in PBMC from patients with more advanced stages of recurrent disease." (PMID 27276714, 2016). "Taken together, these results suggested that SSX2, while associated with changes that occur with EMT, is by itself not a driver of EMT in the context of prostate cancer." (PMID 27276714, 2016).
prostate carcinoma (continued). "In this study, we have identified SSX2 as the predominant SSX family member expressed in prostate cancer, and found its expression in the peripheral blood of 19 of 54 (35%) prostate cancer patients, with expression restricted to circulating tumor cells, and in 7 of 15 (47%) metastatic cDNA samples." (PMID 27276714, 2016). "Similarly, no expression was detected in five normal prostate epithelial cell lines, but SSX2 mRNA was expressed by LAPC4 and MDA-PCa-2b prostate cancer cell lines." (PMID 24681846, 2014). "We have also reported that SSX2 expression can be upregulated selectively in prostate cancer cell lines, but not normal prostate epithelial cells, by treatment with 5-aza-dc." (PMID 20981248, 2010). "Curiously, while overexpression of SSX2 in the LNCaP cell line resulted in modest changes in EMT-associated genes (as expected), we saw low or no change in EMT genes following overexpression of SSX2 in SSX2 negative prostate cancer cell lines." (PMID 27276714, 2016). "We conclude from these findings that SSX2 expression in prostate cancer is not a driver of EMT, but is involved in processes associated with EMT including loss of focal adhesion that may be related to tumor cell dissemination." (PMID 27276714, 2016). "Interestingly, SSX2 mRNA expression was increased by treatment with demethylating agent 5-aza-2′deoxycytidine (AZA) in the prostate cancer cell lines LNCAP and DU145 but not in the normal prostate epithelial cell line RWPE-1." (PMID 24681846, 2014). "Because SSX2 is a CTA, and expressed in recurrent prostate cancer and not normal prostate cells, it is an attractive therapeutic target." (PMID 27276714, 2016).
gastric cancer (4 papers, 2010 to 2024). A primary or metastatic malignant neoplasm involving the stomach. "Studies have shown that BCL2‐associated athanogene 1, melanoma‐associated antigen‐A1, MAGE‐A3, melanoma‐associated antigen‐C2, SSX family member 2, and SSX family member 4 genes are several representative genes that are specifically and highly expressed in stomach cancer." (PMID 32227453, 2020). "The paired CD103+ and CD103− T cell clones isolated from a patient with gastric cancer are characterized by the same T cell antigen receptor (TCR): TRAV8-6 TRAJ30, TRBV6-1 TRBJ2-7, recognizing the SSX-2 tumor antigen." (PMID 38561495, 2024).
multiple myeloma (4 papers, 2010 to 2020). "SSX1, SSX2, and SSX4 are expressed in Hodgkin's lymphoma and head and neck cancer, while SSX1, SSX2, SSX4, and SSX5 are expressed in multiple myeloma." (PMID 27276714, 2016).
leukemia (3 papers, 2010 to 2023). A malignant (clonal) hematologic disorder, involving hematopoietic stem cells and characterized by the presence of primitive or atypical myeloid or lymphoid cells in the bone marrow and the blood. "This screening was conducted to determine the specificity of SSX1, SSX2, and SSX3 in additional cancer tissue samples, including leukemia in males and BC in females." (PMID 37241221, 2023).
brain tumors (2 papers, 2006 to 2010). "SSX expression has also been evaluated by RT-PCR in brain tumors in which SSX1 was only expressed in astrocytomas, while SSX2 was expressed in astrocytomas and oligoastrocytomas, and SSX4 was expressed in both of these as well as oligodendrogliomas." (PMID 20981248, 2010).
hepatocellular carcinoma (2 papers, 2010 to 2023). A malignant tumor that arises from hepatocytes. "High SSX1 and SSX2 expression levels were observed in patients with hepatocellular carcinoma, which suggests that they might be used as a cancer marker." (PMID 37241221, 2023). "SSX2 p41–49 T cells have also been identified in patients with hepatocellular carcinoma (HCC)." (PMID 20981248, 2010).
leiomyosarcoma (2 papers, 2011 to 2022). An uncommon, aggressive malignant smooth muscle neoplasm, usually occurring in post-menopausal women. "Many leiomyosarcomas, particularly uterine leiomyosarcomas, may express CTAs from the SSX family including SSX-2 which has an A*02.01 epitope." (PMID 21331153, 2011).
metastatic prostate carcinoma (2 papers, 2015 to 2016). A carcinoma that arises from the prostate gland and has spread to other anatomic sites. "In fact, a therapeutic vaccine encoding SSX2 as one target antigen has recently opened to accrual for patients with advanced, metastatic prostate cancer (NCT02625857)." (PMID 27276714, 2016). "For instance, expression of SSX2 has been associated with metastatic prostate cancer, advanced tumor stage and malignant tumors." (PMID 25857299, 2015).
soft tissue sarcoma (2 papers, 2017 to 2020). A malignant neoplasm arising from muscle tissue, adipose tissue, blood vessels, fibrous tissue, or other supportive tissues excluding the bones. "We, therefore, aimed to describe the expression of three CTAs, PRAME, NY-ESO-1, and SSX2, and analyze their prognostic value in a large cohort of high-risk soft tissue sarcomas with long-term follow-up." (PMID 33287125, 2020). "In the present study, we analyse the expression of CTAs NY-ESO-1, PRAME, and SSX2 in a large and well-characterised cohort of high-risk soft-tissue sarcoma patients with long-term follow-up and correlate our findings with the presence of TILs, clinical tumour characteristics, and survival data." (PMID 33287125, 2020). "In this study, we analysed the expression of CTAs PRAME, NY-ESO-1, and SSX2 as well as the presence of tumour-infiltrating lymphocytes (TILs) in a well-characterised cohort of high-grade soft tissue sarcoma patients." (PMID 33287125, 2020).
carcinosarcoma (1 paper, 2015). A malignant tumor composed of a mixture of carcinomatous and sarcomatous elements. "More than 90 % of SS present this translocation, which gives rise to a fusion gene, SS18 (SYT)-SSX (SSX1 or SSX2, or both), whereas MPNST and carcinosarcoma lack SS18-SSX fusions." (PMID 26112006, 2015).
colon adenocarcinoma (1 paper, 2023). "The study examined the expression levels of the SSX1, SSX2, and SSX3 genes in NC and colon adenocarcinoma (COAD) tissue samples using RNA sequencing data from the TCGA repository (accessed on 20 February 2023)." (PMID 37241221, 2023).
epithelial-myoepithelial carcinoma (1 paper, 2021). A malignant neoplasm which occurs mostly in the major salivary glands (most frequently in the parotid gland), but also in the minor salivary glands of the oral mucosa and the tracheobronchial tree. "Of those, SSX2 and SS18 have been identified in histology-type investigations in the literature, whilst MVP2 function is little known, while HRAS is implicated in various types of cancers (i.e., salivary duct carcinoma, epithelial myoepithelial carcinoma, etc." (PMID 34359782, 2021).
metastatic disease (1 paper, 2020). "In multivariate analysis, high PRAME and low SSX2 expression levels as well as metastatic disease and non-radical resections were independent predictors of shorter overall survival." (PMID 33287125, 2020). "In multivariate analysis, high PRAME and low SSX2 expression levels as well as metastatic disease, non-radical resections, and not receiving chemotherapy are shown to be independent predictors of shorter overall survival." (PMID 33287125, 2020).
myeloid leukemia (1 paper, 2018). A clonal proliferation of myeloid cells and their precursors in the bone marrow, peripheral blood, and spleen. "Our previous serological analysis of recombinant tumor cDNA expression libraries (SEREX) analysis of AML patient sera, identified SSX2IP and PASD1, as well as SSX2IP’s interacting partner, SSX2, as potential targets for the immunotherapy of myeloid leukemia." (PMID 29423088, 2018).
ovarian tumor (1 paper, 2019). "In addition, aberrant expression of SSX-1, SSX-2, or SSX-4 was identified in 26% of ovarian tumor specimens, and SSX-1, SSX-2, and SSX-4 expression was detected in 2.5%, 10%, and 16% of 120 EOC specimens, respectively." (PMID 30609934, 2019).
prostate tumor (1 paper, 2010). "We have also recently identified SSX2 p103–111 as an SSX2 epitope using HLA-A2 transgenic mice immunized with a genetic vaccine encoding SSX2, and further identified that p103–111-specific CTL can lyse HLA-A2-expressing prostate tumor cells (Smith, manuscript submitted)." (PMID 20981248, 2010).
seminoma (1 paper, 2006). A radiosensitive malignant germ cell tumor found in the testis (especially undescended), and extragonadal sites (anterior mediastinum and pineal gland). "In terms of human testicular tumours, many CT antigens including MAGE, GAGE, PAGE-1, SSX2, NY-ESO-1, LAGE-1, and SCP-1 are also demonstrated to have higher frequency of expression in seminomas than in non-seminomas." (PMID 16479255, 2006).